GDNF (glial cell derived neurotrophic factor)
Diseases named in the same sentence as GDNF in open-access papers (continued):
Sharing a sentence is not in itself a finding about the gene and the disease.
glioma (continued). "We found that GDNF together with its two receptors in autocrine ligand-receptor pairs are highly expressed in glioma neoplastic cells." (PMID 31118022, 2019). "In the present study, the mechanism by which GDNF promotes glioma cell migration and invasion through regulating the dispersion and location of the Golgi apparatus (GA) is described." (PMID 30695072, 2019). "Originally purified from a rat glioma cell line, glial cell-derived neurotrophic factor (GDNF) was shown to promote differentiation and survival of rat midbrain dopamine neurons, increase outgrowth of neurites and dopamine uptake in vitro." (PMID 29973907, 2018). "GDNF was first discovered in the culture medium of glioma cell lines and is considered a member of the transforming growth factor-β (TGF-β) family." (PMID 29751848, 2018). "In low-grade gliomas, it appears that the glial cell-derived neurotrophic factor (GDNF) promotes cell migration through JNK, ERK-1/2, and p38 MAPK signaling pathways." (PMID 30190671, 2018). "The growth factor glial cell–derived neurotrophic factor (GDNF), is secreted in mouse and human gliomas, which serves as a strong chemoattractant for microglia." (PMID 30319362, 2018). "Our findings reveal that GDNF interacts with the extracellular domain of proN-cadherin, which suggests that proN-cadherin mediates GDNF-induced glioma cell migration and invasion." (PMID 28212546, 2017). "We previously demonstrated that hyperacetylation of histone H3K9 in promoter II of glioma cells promotes high transcription of the glial cell line-derived neurotrophic factor (GDNF) gene." (PMID 28187447, 2017). "Egr-1 is a key transcription factor for GDNF gene activation and is involved in histone hyperacetylation-mediated high-level GDNF transcription in glioma cells." (PMID 28187447, 2017). "Treatment of C6 glioma cells with exogenous GDNF resulted in increased expression of NRP1 protein and mRNA." (PMID 29088765, 2017). "In conclusion, we demonstrated that NRP1 was the binding receptor of GDNF in glioma cells with therapeutic potential." (PMID 29088765, 2017). "As it is a powerful factor promoting glioma cell proliferation and migration, GDNF is closely related to glioma development." (PMID 28187447, 2017). "Since GDNF is secreted in high amounts by gliomas, we postulated that GDNF membrane receptors would also be highly expressed in gliomas." (PMID 29088765, 2017). "Further, immunofluorescent (IF) staining showed that exogenous GDNF recruited more NRP1 to the cell membrane of C6 glioma cells, whereas the non-GDNF treated cells showed diffused cytoplasmic staining for NRP1." (PMID 29088765, 2017). "This indicates that the regulation of GDNF induced by overexpressed Egr-1 and RNA POL II in high-grade glioma cells is dependent on histone hyperacetylation of GDNF promoter II." (PMID 28187447, 2017). "Using laser scanning confocal microscopy, we observed that exogenous GDNF recruited NRP1 protein to the C6 glioma cell membrane." (PMID 29088765, 2017). "Although the correlation between GDNF and glioma has received various attentions, the interaction between GDNF and N-cadherin requires deeper exploration." (PMID 28212546, 2017). "The effects of Egr-1 overexpression on histone acetylation, Egr-1 binding to GDNF promoter II, RNA POL II recruitment, and GDNF transcription in curcumin-treated C6 glioma cells were examined by gene overexpression, ChIP, and real-time PCR studies." (PMID 28187447, 2017). "H3K9 acetylation in the Egr-1 binding sites (on-target region −98/+56 bp) and off-target region (−864/−793 bp) of GDNF promoter II was measured in high-grade and low-grade glioma tissues and normal brain tissue using ChIP-PCR." (PMID 28187447, 2017). "Glial cell line-derived neurotrophic factor (GDNF) was originally isolated from a rat glioma cell line and identified as a growth factor promoting the survival of dopaminergic (DA) neurons." (PMID 28493093, 2017).
glioma (continued). "The effects of Egr-1 overexpression on these outcomes were elucidated using a C6 glioma cell model with decreased histone acetylation in GDNF promoter II following treatment with the histone acetyltransferase (HAT) inhibitor curcumin." (PMID 28187447, 2017). "Acetylation was significantly higher in the Egr-1 on-target region of GDNF promoter II (P < 0.01) and the off-target region (P < 0.05) in high-grade glioma tissue compared with normal brain tissue." (PMID 28187447, 2017). "We previously reported that abnormal high-level GDNF transcription in glioma cells was related to histone hyperacetylation in its promoter II rather than gene mutation." (PMID 28187447, 2017). "This is consistent with our previous report of a difference in H3K9 acetylation in GDNF promoter II of rat C6 glioma cells." (PMID 28187447, 2017). "Many studies have confirmed that GDNF also plays important roles in the metastatic and invasive processes of the glioma." (PMID 28212546, 2017). "Our next study will focus on the how Egr-1 and RNA POL II jointly promote high-level GDNF transcription in high-grade glioma cells." (PMID 28187447, 2017). "In this study, we demonstrate that proN-cadherin mediates GDNF-promoted malignant astroglioma cells migration and clarify a novel molecular mechanism underlying glioma cell invasion and migration, which might influence future clinical diagnosis and treatments for glioma." (PMID 28212546, 2017). "RNA POL II binding to the Egr-1 binding sites of GDNF promoter II was measured by ChIP-PCR to assess the recruitment of RNA POL II in the Egr-1 binding sites of GDNF promoter II in different grades of glioma." (PMID 28187447, 2017). "This is consistent with the difference in H3K9 acetylation in GDNF promoter II of rat C6 glioma cells we previously reported." (PMID 28187447, 2017). "CCK8 proliferation assay showed that NRP1 RNAi resulted in decreasing proliferation of C6 glioma cells treated with exogenous GDNF compared to C6 cells transduced with CON77 RNAi (P < 0.05)." (PMID 29088765, 2017). "As the most prevalent primary brain tumor, gliomas are highly metastatic, invasive and are characteristic of high levels of glial cell-line derived neurotrophic factor (GDNF)." (PMID 28212546, 2017). "Recently, a research indicate the hyperacetylation of H3K9 at EGR1 binding sites in promoter region II of the GDNF gene can up-regulate the binding of EGR1 to increase GDNF gene transcription in glioma cells." (PMID 26376677, 2015). "For example, siRNA mediated reduction of glial cell-derived neurotrophic factor (GDNF) in mouse glioma cells diminished attraction of TAMs in vivo." (PMID 24675569, 2014). "Forty-eight hr treatment with progesterone (10 μM) resulted in a significant elevation of GDNF secretion from C6 glioma cells that remained elevated up to 72 hr." (PMID 23493386, 2012). "In the present work, we evaluated the effects of progesterone on GDNF secretion from C6 glioma cells as an in vitro model system." (PMID 23493386, 2012). "Forty-eight hr after the treatment with progesterone (10 μM), the secretion of GDNF was significantly increased from the cultured C6 glioma cells into the medium (P< 0.05)." (PMID 23493386, 2012). "GDNF was shown to be up-regulated in astrocytes during various pathophysiological conditions and proliferative effects on C6 glioma cells have been demonstrated." (PMID 21818353, 2011). "Beyond this, a regulatory mitogenic effect has been demonstrated for rat glioma cells by adding exogenous GDNF or using antisense oligonucleotides for the suppression of endogenous GDNF." (PMID 21203407, 2010). "In the context of gliomas, the literature suggests that the GDNF–RET pathway and FGFR4 signaling may contribute to progression and treatment resistance in subsets of brain tumors." (PMID 41517303, 2025).
glioma (continued). "In the glioma microenvironment, there is a high presence of inflammatory mediators and chemotactic substances, including colony-stimulating figure (CSF-1, -2) and glial cell-derived neurotrophic figure (GDNF)." (PMID 40727443, 2025). "Meanwhile, SERPINE1 was found to be elevated in rat C6 glioma cells treated with GDNF from our early RNA-seq data and enriched in the GO term of wound healing, which indicated that GDNF may accelerate GBM cell migration and invasion through SERPINE1." (PMID 39337713, 2024). "Additionally, glial cell line-derived neurotrophic factor (GDNF), a factor highly expressed in human gliomas, was found to (i) recruit microglial cells to the tumoral site, (ii) significantly increase tumor growth, and (iii) decrease survival in murine models." (PMID 38893093, 2024). "Also, identifying the GDNF translocation mechanism and its contribution to U251 and HA survival and neuroinflammation can help reduce glioma cell proliferation and tumor growth, as GDNF proteins are known to regulate brain cell survival." (PMID 37833789, 2023). "Preliminary data of our group suggest that Neuropilin-1 (NRP1) may be a membrane receptor that mediates the proliferation of C6 glioma cells after exogenous GDNF administration." (PMID 37594930, 2023). "Compared to normal brain tissues, GDNF levels in glioma tissues are increased by five times." (PMID 37594930, 2023). "Testosterone upregulates GDNF to stimulate proliferation, migration, and invasion of glioma cells." (PMID 37833789, 2023). "The discovery of glial cell line-derived neurotrophic factor (GDNF) as a secretion product from the rat B49 glioma cell line in 1993 heralded the arrival of a powerful promotor of dopaminergic cell survival with enormous potential for treating Parkinson’s disease (PD)." (PMID 37410316, 2023). "In addition, calcitriol can enhance the synthesis of glial cell line-derived neurotrophic factor (GDNF) mRNA in C6 glioma cells, which is integral to the development of the dopaminergic and noradrenergic systems." (PMID 38022259, 2023). "However, up to now, it is unclear how GDNF influences this multi-molecular network to promote migration and proliferation of glioma cells." (PMID 37594930, 2023). "Moreover, GDNF plays a regulatory role in glioma progression and is part of a complex multi-molecule network." (PMID 37594930, 2023). "Studies have shown that GDNF significantly induces glioma cell proliferation and migration, while knocking down the expression of GDNF or its receptor GDNF family receptor alpha 1 (GFR alpha 1) could effectively inhibit the pathological progress of glioma." (PMID 37594930, 2023). "In summary, these studies not only revealed the mechanism of action of exogenous GDNF in promoting the proliferation of C6 glioma cells but may also provide a new biological target for the treatment of malignant glioma." (PMID 37594930, 2023). "However, little research has been carried out with regard to the mechanism of high secretory GDNF in GBM glioma tumorigenesis." (PMID 37594930, 2023). "It has shown that GDNF can significantly increase the proliferation and migration of glioma cells." (PMID 37594930, 2023). "Glial cell line-derived neurotrophic factor (GDNF) was initially identified as a glioma cell line-secreted factor that might help fetal ventral midbrain neurons survive in vitro." (PMID 36012155, 2022). "In addition to cytokines, glioma cells also produce the growth factor glial cell–derived neurotrophic factor (GDNF), which plays a critical role in controlling TAM recruitment to the TME through GDNF family receptor alpha 1 and 2 expressed by TAMs." (PMID 34503065, 2021). "Interestingly, depleting GDNF in a glioma cell line and implanting the cells in mouse brains shows reduced tumor size and prolonged survival of the mice." (PMID 34503065, 2021). "Glial cell line-derived neurotrophic factor (GDNF) triggers glioma cell migration and invasion." (PMID 34055798, 2021).
glioma (continued). "It has also been shown that GDNF promotes the survival, activation, proliferation, and migration of several glioma cell lines, suggesting that GDNF release could be important for glioma formation." (PMID 34199968, 2021). "Furthermore, there was about five times higher GDNF level detected in human glioma mass in comparison to normal brain tissue." (PMID 34439380, 2021). "GDNF promotes glioma migration and progression in an autocrine manner." (PMID 33511267, 2020). "In an animal experiment, the GDNF stimulation of rat glioma cells increased the expression of PCNA and Ki-67 and enhanced the proliferation of tumor cells, and in our research, the expression of both PCNA and Ki-67 were increased in patients with nonlocal recurrence." (PMID 33585189, 2020). "Glial cell line-derived neurotrophic factor (GDNF) promotes glioma development process." (PMID 30695072, 2019). "It has been identified GDNF promotes migration and invasion of glioma cells." (PMID 30695072, 2019). "In our study, it was observed that GDNF could promote glioma cell migration and increase the expression of GA-related proteins." (PMID 30695072, 2019). "This suggested that GA is a prerequisite for directed glioma cell migration with GDNF treatment." (PMID 30695072, 2019). "In addition, we previously found that GDNF transcription was significantly decreased by the knockdown of Egr-1 in C6 glioma cells." (PMID 28187447, 2017). "We observed decreased proliferation in GDNF-stimulated C6 glioma cells when NRP1 was knocked down." (PMID 29088765, 2017). "Moreover, Egr-1 overexpression has been shown to significantly promote the infiltration and migration of high-grade glioma cells, which is consistent with the biological effect induced by the high-level GDNF transcription." (PMID 28187447, 2017). "This indicates that highly expressed Egr-1 may be involved in regulating the high-level transcription of GDNF in high-grade glioma cells." (PMID 28187447, 2017). "Hence, NRP1 and NRP2 were identified as candidate special receptor of GDNF in C6 glioma cells and we chose to further investigate NRP1 in this study." (PMID 29088765, 2017). "This suggested that NRP1 interaction with exogenous GDNF promoted proliferation of C6 glioma cells." (PMID 29088765, 2017). "Therefore, to identify the membrane receptors for GDNF in GBM, we perfomed a GST pull-down experiment in combination with LC-MS/MS and analyzed the membrane proteins binding to GDNF in C6 glioma cells and normal primary astrocytes, respectively." (PMID 29088765, 2017). "RNAi knockdown of NRP1 reduced proliferation of C6 glioma cells when stimulated with GDNF." (PMID 29088765, 2017). "GDNF mRNA expression was significantly increased by Egr-1 overexpression in C6 glioma cells." (PMID 28187447, 2017). "The effect of Egr-1 overexpression on GDNF transcription in glioma cells was examined to test this hypothesis." (PMID 28187447, 2017). "We therefore hypothesized that Egr-1 expression might also be abnormally increased in high-grade glioma cells and that this transcription factor could mediate histone hyperacetylation-induced high-level GDNF transcription." (PMID 28187447, 2017). "This shows that proN-cadherin mediated GDNF-induced glioma cell invasion and migration." (PMID 28212546, 2017). "Indeed, our previous studies showed that both histone hyperacetylation and CpG hypermethylation occurred in the Egr-1 binding sites of GDNF promoter II in high-grade glioma cells." (PMID 28187447, 2017). "Therefore, in this study, we used a combination of GST pull-down assays with mass spectrometry (MS) and bioinformatic methods to identify the membrane receptor for GDNF on rat C6 glioma cells." (PMID 29088765, 2017). "Therefore, we postulate that the recruitment of NRP1 to the C6 glioma cell membrane is necessary for effective GDNF signaling." (PMID 29088765, 2017).
glioma (continued). "It has been shown that nanomolar concentrations of melatonin induced the transcription of glial cell line-derived neurotrophic factor (GDNF) mRNA in C6 glioma cells, and that micromolar concentrations of melatonin protected C6 glioma cells from amyloid-β-induced apoptosis." (PMID 24137328, 2013). "Moreover, the expression level of the GDNF protein was negligible in C6 glioma cells transfected with the ARE-containing GDNF expression vector." (PMID 22248285, 2012). "Our findings demonstrate that progesterone is able to elevate GDNF secretion from C6 glioma cells." (PMID 23493386, 2012). "Furthermore, the mouse GDNF construct that included the ARE sequences following the coding region led to marginal expression of the GDNF protein in transfected C6 glioma cells." (PMID 22248285, 2012). "This background prompted us to investigate whether progesterone is able to stimulate GDNF secretion from C6 glioma cells." (PMID 23493386, 2012). "Thus, GDNF may contribute to glioma migration and invasion and play the role of a potential molecular link in the association between PD and glioma." (PMID 38612708, 2024). "Furthermore, we investigated the effect of GDNF on the proliferation in rat C6 glioma cells." (PMID 37594930, 2023). "The forest plot shows that EPB41L4A.AS1, GDNF.AS1, HAR1A, LINC00237, SLC25A21.AS1, SNA13.AS1, and WDFY3.AS2 are the protective factors with HR < 1, while LINC00092, LINC00265, LINC00339, LINC00665, PAXIP1.AS2, SNHG16, SNHG9 and SOCS2.AS1 are risk factors with HR>1 in glioma patients." (PMID 35273128, 2022). "Therefore, we further hypothesized that Egr-1 might be involved in histone hyperacetylation-mediated GDNF transcription in high-grade glioma cells by increasing RNA POL II recruitment to the Egr-1 binding sites of GDNF promoter II." (PMID 28187447, 2017). "GDNF, a member of the transforming growth factor-beta (TGF-β) superfamily, was first isolated from the rat B49 glioma cell line." (PMID 39337713, 2024). "5-HT can induce the expression of glial cell line-derived neurotrophic factor (GDNF) in glioma cells, which is an important prerequisite for the initiation and development of glioma." (PMID 37759283, 2023). "Astrocytes mediate paracrine secretion through glial cell-derived neurotrophic factor (GDNF) and RET (Rearranged during Transfection) signaling to regulate glioma cell invasion." (PMID 36825022, 2023). "In this study, we explored the relationship between GDNF, NF-κB, CXCL1, and cell proliferation and proved that GDNF promoted C6 glioma cell proliferation through the NF-κB/CXCL1 signaling pathway." (PMID 37594930, 2023). "And exogenous glial cell line-derived neurotrophic factor (GDNF) induced proliferation and up-regulated the level of CXCL1 in rat C6 glioma cells determined by sqPCR and ELISA." (PMID 37594930, 2023). "This is in line with several studies, which showed that valproates significantly increase GDNF and BDNF expression in rat C6 glioma cells and astrocytes." (PMID 38069144, 2023). "On the other hand, glioma-cells release chemoattractant molecules that recruit TAMs and promote tumor growth: CCL2, CCL7 (or MCP-3), IL-33, GDNF (Glial cell line-derived neurotrophic factor), MCP-1 (CCL2), SDF-1 (CXCL12), CSF-1 (M-CSF), GM-CSF, and EGF." (PMID 35269652, 2022). "NRP1 was also shown to function as a receptor for glial-derived neurotrophic factor (GDNF) in GBM, promoting proliferation of the glioma cells." (PMID 36203599, 2022). "The glioma microenvironment is enriched with inflammatory mediators/chemotactic factors such as monocyte chemoattractant proteins (MCP-1, -3), glial cell-derived neurotrophic factor (GDNF), and colony-stimulating factor (CSF-1, -2)." (PMID 34439380, 2021). "GDNF-dependent activation of ERK-1/2, JNK, and p38 MAPK has been shown to be another mechanism of glioma development." (PMID 34439380, 2021).